CD4 (CD4 molecule)
Diseases named in the same sentence as CD4 in open-access papers (continued):
Sharing a sentence is not in itself a finding about the gene and the disease.
infection (continued). "At this stage, CD4 count at lees than 200, the infection manifests the obvious demonstrations." (PMID 31665007, 2019). "In contrast, CD4 KO mice are able to control infections at levels similar to wild type animals for virtually all pathogens investigated, including viral, bacterial, and parasite infections." (PMID 31781092, 2019). "Finally, the sialic acid-binding immunoglobulin-like lectin Siglec-1 was shown to bind the host-derived ganglioside GM3 that is incorporated into the viral membrane and is a key interaction involved in HIV-1 transfer to CD4+ T cells via trans-infection." (PMID 31708924, 2019). "In both μMT and WT mice, we observed high levels of CD4 T-cells in the lungs during infection." (PMID 31641151, 2019). "Interestingly, we found that the anti-CD235a antibody significantly abrogated the trans-infection of HIV-1 by CECs to already activated autologous CD4+ T cells." (PMID 31772057, 2019). "The increased infection observed in cells obtained post exercise supports the hypothesis that there was increased metabolic activity in CD4+ T cells following acute bouts of resistance exercise." (PMID 31552706, 2019). "Although the basal levels of this population were higher in C57BL/6 animals, 2 weeks post-infection this CD4 subset significantly increased in BALB/c and SV/129 mice, while it did not change in C57BL/6 mice (p ≤ 0.05 or p ≤ 0.01, compared with BALB/c or SV/129, respectively)." (PMID 30881923, 2019). "Such infection-primed CD4 T cells may have priority for persistence as they were generated in the context of a robust inflammatory response and activation of many cells in the innate compartment." (PMID 31134060, 2019). "Similarly, restriction to cutaneous route of infection was also seen with GM-CSF–producing CD4+ T cells in mice infected with HSV-2." (PMID 31356170, 2019). "We noticed that both CD4+ T cell-depleted and isotype control animals challenged with H99 cells maintained or increased in body weight over time, while the unvaccinated ones lost weight rapidly following infection." (PMID 31772051, 2019). "Also complicating estimation of the diversity of the primary response of human CD4 T cells to infection are limitations in sampling tissues that are at the site of the response." (PMID 31134060, 2019). "Additionally, these proteins contain the capsid region of DENV, which is one of the main targets of cytotoxic and IFNγ-secreting CD4+ T cells, generated during a natural infection." (PMID 31507591, 2019). "If Env encounters CD4 in the infected, virion-producer cell, then conformational changes expose epitopes on Env that are otherwise only briefly exposed on virions during the infection of target cells." (PMID 31480747, 2019). "Therefore, CD4+ T-cell responses in the spleen were analyzed by flow cytometry upon infection of mice with S. aureus USA300 WT or USA300 Δαβδ mutant strain for 72 h or treatment with PBS." (PMID 31134074, 2019). "However, anti-CD35 antibody to some extent but rCCL-5 almost abrogated HIV-1 trans-infection from RBCs of uninfected CD4+ T cells." (PMID 31772057, 2019). "CD4 T cell proliferation responses to viral peptides were significantly different between primary and rechallenge infections for weeks 2 (P = 0.034), 3 (P = 0.015) and 4 (P = 0.037) where higher CD4 T cell responses were observed for rechallenged survivor cats." (PMID 31118053, 2019). "Of note, aside from pDCs and macrophages, other leukocytes such as B cells and neutrophils do not appear to accumulate in SIV-infected cervical tissue or co-localize with clusters of SIV-RNA+ or CD4+ T cells, suggesting CD4+ T cell recruitment is the main chemotactic role pDCs have during infection." (PMID 31156637, 2019). "Thus, depletion of NK cells prior to LMV-Cl13 infection results in enhanced effector function of CD4+ and CD8+ T cells, leading to a significant reduction of viral titres during the later stages of infection." (PMID 30791575, 2019).
infection (continued). "In addition to duration of infection, high viral load and low CD4+ T cell count were the strongest predictors for the development of bNAb responses in previous studies." (PMID 31027215, 2019). "Given the increasing evidence that ZIKV can be transmitted via sexual contact, we were also interested in determining whether a protective CD4+ T cell response is activated via this route of infection." (PMID 30677097, 2019). "Given that T cell clonal expansion is a fundamental aspect of mounting a strong response to infection, we further investigated whether developmental exposure changes CD4+ T cell proliferation using in vivo and ex vivo approaches." (PMID 31391494, 2019). "Acknowledging its small size (n = 4), our extensive longitudinal study represents the first time that the major immune correlates of protection in RV144 were identified as being also associated with control of disease progression and maintaining CD4/CD8 ratios in natural infection." (PMID 31139189, 2019). "Further, seven human plasma chemokines were assessed, and fold-change in CXCL10 (HIV+ vs. HIV− plasma level) was significantly higher in HIV rapid progressors, with CXCL10 level during PHI negatively correlated with CD4+ T-cell counts at the 4-month-infection point." (PMID 31836011, 2019). "Residential pattern of the CD4+ Trm cells in our study was different from the prevailing view that after resolution of infection/inflammation, CD4+ Trm cells are preferentially localized within parenchymal tissues, while CD8+ Trm cells adhere to epithelial layers." (PMID 31156652, 2019). "Finally, viruses produced in the MΦ-QVOAs were replication competent and capable of producing de novo infection of CD4 T cells." (PMID 31431552, 2019). "Similarly, lymphocytic choriomeningitis virus (LCMV), following infection in mice, is primarily restricted to thymic CD4+ T cells, with only marginal involvement of cytotoxic CD8+ T cells, causing suppression of virus-specific T cell responses." (PMID 31505755, 2019). "Alternatively, an increased antiviral state in CD4+ cells which reduced their capacity to initiate productive infection following intrarectal challenge may have been established." (PMID 31413132, 2019). "In addition, given that PN is reported to have a positive predictive value for a CD4 count of <200 among HIV patients, PN patients are also likely to be at greater risk of infection because of more frequent rates of immunosuppression." (PMID 31405223, 2019). "Persistent antigenic exposure appears to be the main driver of this phenotype as suggested by infection models with Mycobacterium tuberculosis, which demonstrate that the temporal availability of antigen affects cytokine expression and magnitude of the CD4+ T cell response." (PMID 31379821, 2019). "The significance of macrophage infection in viremic individuals is well established: HIV species within individuals become increasingly macrophage-tropic with disease progression and by late stage infection, CD4 T cells are depleted and infected macrophages are a principal reservoir driving viremia." (PMID 31297114, 2019). "The CD4+ T-cell count is a key factor in relation to the risk of infection in PLWH, even in HIV-infected patients on cART, since a dysregulation of the immune system predisposes an individual to invasive infections and the development of IE." (PMID 31382658, 2019). "Although HIV completely inhibits the IRF3-mediated IFN-I response in myeloid DCs, macrophages and CD4+ T cells upon uptake or infection, pDCs constitutively express high levels of IRF7 and upon sensing endosomal HIV ssRNA through TLR7, IFN-I production is rapidly and potently induced." (PMID 31156637, 2019). "Moreover, we observed that mice receiving ctrl.-Ig upregulate the expression of CTLA-4 on the surface of CD4+ T cells during infection in contrast to CTLA-4-Ig-treated mice." (PMID 31950032, 2019).
infection (continued). "Within each analysis stratified by stage of infection at diagnosis, we also included CD4+ count at the time of viral load measurement as a covariate, because CD4+ levels will decrease as disease progresses, accounting for additional variance in viral load due to time since infection." (PMID 31857582, 2019). "Furthermore, at later stage of the infection a higher percentage of Mtb specific CD4+PD1+ T lymphocytes were found in the lungs of mice immunized with CAF01+H56 and RA." (PMID 31130946, 2019). "CD4+ T cell responses to aerosol Mtb challenge are characterized by a delayed recruitment of effector T cells in the lungs, potentially hampering the host's response to infection and permitting the bacteria to establish a persistent infection." (PMID 31293568, 2019). "Given that the magnitude of the CD4 T cell recall response was unaltered during re-infection, we hypothesized that celecoxib treatment induced changes in the phenotype/quality of the T cell response." (PMID 31396568, 2019). "While the mechanism for the immunity is unclear, C. trachomatis infection has been associated with the formation of follicles 78; the presence of IFN‐γ+ CD4+ T cells in these follicles has been thought to provide an immune response in the case of a secondary infection." (PMID 31468677, 2019). "All drugs were used at concentrations that blocked direct HIV-1 cis infection of CD4+ T cells." (PMID 31304185, 2019). "For example, SP-A was shown to bind to HIV, thereby protecting CD4+ cells from direct infection." (PMID 31817644, 2019). "In this study, we asked whether HA epitopes recognized by CD4 T cells in the primary response to infection are equally distributed across the HA protein or if certain segments are enriched in CD4 T cell epitopes." (PMID 31694141, 2019). "While the main HIV cellular target, activated CD4+ T cells, die massively during the initial infection, it is assumed that a very low proportion of the initially infected cells live long enough to be able to enter into a resting state (quiescence), establishing a memory reservoir." (PMID 31628331, 2019). "The natural infection or exposure to B. anthracis induces the expansion and differentiation of specific T-cells, with growing evidence that cellular immune responses involving IFNγ-producing CD4+ T-cells contribute significantly to protective immunity." (PMID 31213220, 2019). "Here we show that HIV-1 trans infection of CD4+ T cells by 2 types of APCs, DCs and B lymphocytes, is insensitive to virus-suppressive levels of ART, that is, darunavir, rilpivirine, and maraviroc; rilpivirine, and to some extent tenofovir treatment in vitro, showed a limited effect." (PMID 31304185, 2019). "Interestingly, infected TEC cells transmitted the HTLV-1 virus to CD4+ cells, functioning as a reservoir of the infection." (PMID 31505755, 2019). "Fas-induced apoptosis may occur in viral-infected cells via binding of FasL on CD8+ T cells, and may be upregulated in this study as a result of increased infection of CD4+ lymphocytes in prednisolone- and CsA-treated animals." (PMID 31480322, 2019). "Moreover, the reduced activation of effector/memory CD4+ and CD8+ T cells associated with increased numbers and frequency of CD4+CD25+Foxp3+ Tregs at the site of infection demonstrated the important role of dectin-1 in defining the severity of pulmonary PCM." (PMID 30067137, 2019). "As only 10% of CD4+RORγt+ T cells from patients with infection expressed IL-23R, this suggests that activation of a relatively small proportion of the potential pool of CD4+ Th17 cells is required to control infection." (PMID 31658288, 2019). "Our findings demonstrate both in an in vitro model and ex vivo studies that NP-Beclin 1 and NP-vFLIP-α2 can induce the selective killing of latent HIV-infected resting memory CD4+ T cells, while sparing uninfected cells and preventing new infection of bystander cells." (PMID 31142734, 2019).
infection (continued). "Infection of TAP1−/− mice results in reduced CD4 T cell IFNγ production." (PMID 30873151, 2019). "Also, the set point CD4 count of this animal remains extremely high throughout the infection; its set point CD4 count is higher than 700 cells/μL8, while the maximum set point CD4 count of all other animals in the morphine group is 39 cells/μL8." (PMID 30931971, 2019). "We investigated whether HIV-2 reservoirs might follow the peculiar distribution reported in models of attenuated HIV-1/SIV infections, i.e. limited infection of central-memory CD4 T lymphocytes (TCM)." (PMID 31095640, 2019). "Indeed, production of gamma interferon (IFN-γ), tumor necrosis factor (TNF), and interleukin-2 (IL-2) by CD4+ T cells has been associated with preerythrocytic protection following CPS immunization and natural infection." (PMID 30787114, 2019). "In addition, we separated CD69+ and CD69− CD4+ T cells from fresh cervical suspensions, which we immediately infected to evaluate infection (p24) and CD69 expression." (PMID 31628331, 2019). "Thirteen variables were identified as independent risk factors for CRKP infection, including KP colonization or infection in the preceding year (OR=3.32, 95% CI 2.01-4.38), CD4/CD8 ratio <1 (OR=2.98, 95% CI 2.02-4.19), and parenteral nutrition ⩾48 h (OR=1.88, 95% CI 1.22-3.04)." (PMID 31032370, 2019). "Here, we could detect an elevated PD-1/TIGIT co-expression on HCV-specific CD4+ T cells of acutely and chronically infected patients compared to patients with spontaneously resolved infections." (PMID 31337800, 2019). "Furthermore they are most efficient at HIV uptake, support the highest levels of infection and are the most efficient at transferring HIV to CD4 T cells, after de novo infection." (PMID 31227717, 2019). "It is suggested that the active infection influences the CD4+ T-cell counts of ART-naïve individuals, which could explain the improvement in the prognosis of HIV-1-infected individuals." (PMID 31309117, 2019). "Furthermore, natural infection or immunization with the wP vaccine induced CD69+CD4+ TRM cells that secreted IL-17, IFN-γ or both cytokines, indicative of polyfunctional memory T cells." (PMID 30866771, 2019). "To address the role played by the IL-21/IL-21R signaling axis in CD4+ T cells in host protection after C. rodentium infection, we assessed the bacterial burden, the infection kinetics and survival rates in conditional knockout mice with a CD4+ T cells-specific deletion of STAT3 activity." (PMID 30818341, 2019). "Interestingly, there appears to be a positive correlation between the antiviral potential of the lectins in both primary infection and co-cultivation assays, and the binding of the lectins to gp120, gp41 and CD4." (PMID 30996857, 2019). "This led to the hypothesis that anti-V2 Abs in vivo block viral adhesion and subsequent infection of Th17 cells expressing CD4, CCR5, and α4β7." (PMID 31390725, 2019). "In addition, we analyzed the viral load at day 15 post Cl13 infection in either Tcf7fl/fl-CD4Cre mice or WT mice after excluding the CD4 T cell influence via injection of the CD4 T cell-depleting antibody GK1.5 at 1 day before infection." (PMID 30814995, 2019). "Moreover, other man-specific seaweed lectins were used as blocking agents for the infection in vitro of CD4+ T-lymphocytes by HIV-1." (PMID 31357490, 2019). "However, when we measured infection from 293T cells to 293T/CD4/X4 cells, the effect of Vpu deletion on HIV-1 infectivity remained the same (Zotova & Mazurov, unpublished data)." (PMID 31027334, 2019). "It indicated that both CD103-expressing CD4+ and CD8+ T cells were involved in the infection induced pulmonary inflammation, and CD4+ Th cells might exhibit more function in this process." (PMID 31775660, 2019). "We thus hypothesized that during HIV-1 chronic infection, cross-reactive CD8 T cells responding to AE might promote DC maturation and facilitate HIV-1 trans-infection from DCs to CD4 T cells." (PMID 31398241, 2019).
infection (continued). "SHIV AD8-EO was derived by five serial-macaque passages followed by further adaption in macaque PBMCs while SHIV Q23AE was generated from a HIV-1 Env from early in infection and then modified with a single amino acid substitution (A204E) to allow the Env to use macaque CD4 for entry." (PMID 31260493, 2019). "Thus, during enteric T. spiralis infection, enhanced TGFβ activation by integrin αvβ8 on DCs is important in triggering infection-induced TGFβ signalling pathways in CD4+ T-cells, driving Th17 cells, and maintaining Treg numbers during homeostasis." (PMID 30998782, 2019). "Finally, the amount of input virus loaded into DCs and B cells for assessing trans infection was chosen to be highly inefficient for productive infection of CD4+ T cells in cis." (PMID 31304185, 2019). "Moreover, ex vivo DCs and B cells from ART-suppressed PWH mediated efficient HIV-1 trans infection of CD4+ T cells, which were resistant to direct cis infection." (PMID 31304185, 2019). "We also assessed the memory phenotype of the infected cells and observed that productively infected CD4+ T cells were more likely to display a transitional memory phenotype than their uninfected counterparts, as previously reported in in vitro infection studies." (PMID 30811499, 2019). "Since T cell activation is required for productive infection, we first assessed whether CD4+ T cells displaying an activated phenotype were enriched in productive HIV." (PMID 30811499, 2019). "We found that an intact IL-21/IL-21R axis was required for resistance against and clearance of enteric infection with this pathogen and that activated CD4+ T cells were the exclusive expressors of IL-21 following infection with C. rodentium in the distal colon." (PMID 30818341, 2019). "Accordingly, local genital administration of IL-12 encapsulated in sustained-release microparticles during gonococcal infection induced Th1-dependent immune responses with the production of IFNγ by CD4+ T cells and anti-gonococcal antibodies, and accelerated clearance of the infection." (PMID 31681305, 2019). "CCR5+, Ki67+, or Ki67+/α4β7+ CD4+ T cells in peripheral blood prior to challenge were not correlated with susceptibility to infection or protection." (PMID 30552025, 2019). "In addition, in contrast to cells localized to the lung, that are enriched for IFN-γ, IL-2 is reliably expressed by CD4 T cells elicited by infection that localize to secondary lymphoid tissue." (PMID 31694141, 2019). "However, we found both, a significant increase of the proportion of recent infections and an increase in CD4+ T-cell count among the new HIV diagnoses over the study period, from 2008 to 2014." (PMID 30899060, 2019). "Comparatively, 96% of Huh7 cells were positive for EBOV antigens whereas only ~5% of Jurkat cells were positive for EBOV antigens further suggesting that although viral synthesis occurs in CD4+ T cells, the rate of infection and/or protein synthesis is significantly lower." (PMID 31648236, 2019). "We investigated whether this infection might follow peculiarities associated with other models of attenuated HIV-1/SIV infection, i.e. a limited infection of a key subset of memory CD4 T lymphocytes, the central-memory ones (TCM)." (PMID 31095640, 2019). "As predicted, this resulted in the generation of serum and genital anti-gonococcal antibodies, IFNγ production by CD4+ T cells, the establishment of immune memory that can be recalled by challenge infection 1–6 months later, and faster clearance of the challenge infection." (PMID 31681305, 2019). "This study also found that infection of CD4+ T cells with HIV increased transcription of the gene encoding HLA-F; our finding suggests this may be due to an epigenetic mechanism." (PMID 31324826, 2019). "Furthermore, at 8 weeks post-infection, the percentage of splenic CD4+ T cells showing the potential to secrete IL-10 was significantly and tendentiously increased in BALB/c and SV129 mice, respectively." (PMID 30881923, 2019).